ZNF648 (zinc finger protein 648)
Description:
May be involved in transcriptional regulation.
Synonyms: FLJ46813
Tractability: No criterion of Open Targets' tractability assessment is met for any kind of drug.
Gene: Protein-coding gene on chromosome 1 (182,054,570 to 182,061,712, reverse strand). Ensembl gene ENSG00000179930.
Subcellular location: Nucleus
Gene Ontology:
Molecular function: protein binding; DNA-binding transcription factor activity, RNA polymerase II-specific; RNA polymerase II cis-regulatory region sequence-specific DNA binding
Biological process: regulation of DNA-templated transcription; regulation of transcription by RNA polymerase II
Cellular component: nucleus
Genetic constraint (gnomAD): Loss-of-function variants: 3 observed, 3.07 expected, observed/expected ratio (o/e) 0.98, 90% interval 0.42 to 1.85. That is too few expected variants to judge how well the gene tolerates losing a copy. Missense variants: 874 observed, 779.58 expected, observed/expected ratio (o/e) 1.12, 90% interval 1.06 to 1.19. Synonymous variants: 376 observed, 335.03 expected, observed/expected ratio (o/e) 1.12, 90% interval 1.03 to 1.22.
Homologues: Orthologues: chimpanzee ZNF648 (99% identical), macaque ZNF648 (93% identical), dog ZNF648 (78% identical), mouse Zfp648 (65% identical), rat Zfp648 (64% identical), pig ZNF648 (50% identical), zebrafish znf648 (34% identical), Drosophila melanogaster CG18476 (20% identical), Drosophila melanogaster CG10669 (19% identical). Paralogues in human: ZNF808 (27% identical), ZFP62 (26% identical), ZNF721 (25% identical), ZNF485 (21% identical), ZNF664 (12% identical).
Diseases named in the same sentence as ZNF648 in open-access papers:
ZNF648 is named in the same sentence as 4 diseases in open-access papers, as found by Europe PMC text mining. Sharing a sentence is not in itself a finding about the gene and the disease.
ZNF648 shares sentences with these, for which no sentence is quoted: Cirrhosis (1 paper); Cognitive impairment (1); coronary artery disease (1); preeclampsia (1).